ESRG (embryonic stem cell related)
Synonyms: HESRG
Gene: Long non-coding RNA gene on chromosome 3 (54,632,109 to 54,657,002, reverse strand). Ensembl gene ENSG00000265992.
Subcellular location: Nucleus
Diseases named in the same sentence as ESRG in open-access papers:
ESRG is named in the same sentence as 22 diseases in open-access papers, as found by Europe PMC text mining. Sharing a sentence is not in itself a finding about the gene and the disease. The quoted sentences say what the papers report.
embryonal carcinoma (2 papers, 2021 to 2024). A non-seminomatous malignant germ cell tumor characterized by the presence of large germ cells with abundant cytoplasm resembling epithelial cells, geographic necrosis, high mitotic activity, and pseudoglandular and pseudopapillary structures formation. "However, the potential of ESRG as a biomarker has been stated by just one study concerning intracranial germinoma and embryonal carcinoma." (PMID 39310490, 2024). "Furthermore, ESRG is expressed in human PSCs, including embryonic carcinoma cell (ECC) lines, but is silenced in four cancer cell lines and ten cell lines derived from normal tissues." (PMID 34033652, 2021).
breast invasive carcinoma (1 paper, 2024). "The analysis of the ESRG expression using the TIMER2.0 database showed a significant upregulation in breast invasive carcinoma (BRCA), COAD, and LUSC with p<0.001, in addition to bladder urothelial carcinoma (BLCA), lung adenocarcinoma (LUAD), READ, and UCEC with p<0.01." (PMID 39310490, 2024).
cervical squamous cell carcinoma (1 paper, 2024). A squamous cell carcinoma arising from the cervical epithelium. "Further analysis using the UALCAN database showed that ESRG was significantly upregulated in cervical squamous cell carcinoma (CESC), COAD, esophageal carcinoma (ESCA), LUSC, READ, uterine corpus endometrial carcinoma (UCES), head and neck squamous cell carcinoma (HNSC)." (PMID 39310490, 2024).
colon adenocarcinoma (1 paper, 2024). "HESRG: embryonic stem cell-related gene; COAD: colon adenocarcinoma; Coef: coefficient; HR: hazard ratio; 95%CI_l: lower 95% confidence interval; 95%CI_u: upper 95% confidence interval; p: p-value; sig: significance." (PMID 39310490, 2024).
colorectal cancer (1 paper, 2024). A primary or metastatic malignant neoplasm that affects the colon or rectum. "The significant upregulation in COAD and READ aligns with the findings of another study which revealed that ESRG showed an aberrant upregulation in colorectal cancer using quantitative polymerase chain reaction (qPCR) and explored a negative correlation with overall survival." (PMID 39310490, 2024).
esophageal adenocarcinoma (1 paper, 2024). A malignant tumor with glandular differentiation arising predominantly from Barrett mucosa in the lower third of the esophagus. "We noticed that the majority of ESRG mutations occurred in esophageal adenocarcinoma with deep deletion mutation frequency = 3.3% (six cases)." (PMID 39310490, 2024).
glioblastoma multiforme (1 paper, 2024). "Although ESRG expression was significant in glioblastoma multiforme (GBM) and thyroid carcinoma (THCA) with p<0.001, the results do not show whether the gene is upregulated or downregulated in a clear way." (PMID 39310490, 2024).
glioma (1 paper, 2024). A benign or malignant brain and spinal cord tumor that arises from glial cells (astrocytes, oligodendrocytes, ependymal cells). "HESRG: embryonic stem cell-related gene; LGG: brain lower grade glioma; Coef: coefficient; HR: hazard ratio; 95%CI_l: lower 95% confidence interval; 95%CI_u: upper 95% confidence interval; p: p-value; sig: significance." (PMID 39310490, 2024).
lung squamous cell carcinoma (1 paper, 2024). "HESRG: embryonic stem cell-related gene; LUSC: lung squamous cell carcinoma; Coef: coefficient; HR: hazard ratio; 95%CI_l: lower 95% confidence interval; 95%CI_u: upper 95% confidence interval; p: p-value; sig: significance." (PMID 39310490, 2024).
Obesity (1 paper, 2024). Accumulation of substantial excess body fat. "Based on weight, the expression of ESRG was significant in patients with normal weight (p = 1.60e-02), extreme weight (p = 9.58e-03), and obesity (p = 8.70e-03)." (PMID 39310490, 2024).
rectum adenocarcinoma (1 paper, 2024). An adenocarcinoma arising from the rectum. "HESRG: embryonic stem cell-related gene; READ: rectum adenocarcinoma; Coef: coefficient; HR: hazard ratio; 95%CI_l: lower 95% confidence interval; 95%CI_u: upper 95% confidence interval; p: p-value; sig: significance." (PMID 39310490, 2024).
skin cutaneous melanoma (1 paper, 2024). "Moreover, the expression of ESRG in skin cutaneous melanoma (SKCM) tumor tissues was found to be significant with p<0.001." (PMID 39310490, 2024).
uterine corpus endometrial carcinoma (1 paper, 2024). A endometrial carcinoma (disease) that involves the body of uterus. "HESRG: embryonic stem cell-related gene; UCEC: uterine corpus endometrial carcinoma; Coef: coefficient; HR: hazard ratio; 95%CI_l: lower 95% confidence interval; 95%CI_u: upper 95% confidence interval; p: p-value; sig: significance." (PMID 39310490, 2024).
cancer (3 papers, 2021 to 2024). A tumor composed of atypical neoplastic, often pleomorphic cells that invade other tissues. "This study aimed to evaluate the prospective diagnostic and prognostic values of ESRG in various human cancers." (PMID 39310490, 2024). "The genetic alterations in ESRG were analyzed using the cBioPortal platform for cancer genomics using TCGA datasets, we found that ESRG was mutated in 0.77 (<1%) of the queried samples (10,967 samples from 32 studies)." (PMID 39310490, 2024). "On top of that, the study demonstrates the association between ESRG expression and immune cell infiltrations across various cancers including COAD, LUSC, READ, UCEC, and LGG." (PMID 39310490, 2024). "Our results provide a foundation for exploring the association between ESRG expression and the abundance of immune cells considering their complex interaction with patients' survival in different cancer types to be further investigated." (PMID 39310490, 2024). "In this study, we have conducted a comprehensive pan-cancer analysis of ESRG expression including clinicopathological correlation, immune infiltration, and genetic alterations to determine the diagnostic and prognostic value of ESRG using various databases." (PMID 39310490, 2024). "Additionally, genetic alterations analysis using the cBioPortal platform revealed that ESRG mutations are rare across different cancer types, with deep deletion mutations being the most prevalent." (PMID 39310490, 2024). "Moreover, the study primarily focuses on ESRG expression levels and their association with clinical outcomes in different cancers, ignoring the potential regulatory mechanisms and interactions with other molecular pathways." (PMID 39310490, 2024). "However, the association between ESRG expression and cancer is still being studied." (PMID 39310490, 2024). "Based on our findings, the significant upregulation of ESRG in these cancers COAD, LUSC, READ, and UCEC implies its role in carcinogenesis." (PMID 39310490, 2024). "It provides a comprehensive analysis to elucidate the correlation between ESRG expression and its role in cancer development and progression across various types of cancers." (PMID 39310490, 2024). "The paper investigates the role of ESRG, a lncRNA in various cancers." (PMID 39310490, 2024). "Additionally, the functional roles of ESRG in immune regulation and cancer progression remain incompletely understood and need further investigation." (PMID 39310490, 2024). "The expression of ESRG in the cancer cell population might indicate the presence of cancer stem cell potentials; this has been further justified by its critical role in sustaining pluripotency and self-renewal capacity in hPSCs through numerous mechanisms." (PMID 39310490, 2024). "Moreover, our findings figured out relatively significant variations in ESRG expression between normal and different cancer stages in COAD, LUSC, and READ." (PMID 39310490, 2024). "We employed multiple bioinformatics tools and databases to analyze ESRG expression levels, their correlation with clinicopathological parameters and immune cell infiltrations, prognostic value, and genetic alterations across different cancer types." (PMID 39310490, 2024). "However, these significant variations within cancer stages may explore the potential role of ESRG in tumor progression which needs to be further studied." (PMID 39310490, 2024). "Materials and methods: The expression of ESRG in various cancers was analyzed using the Gene Expression Profiling Interactive Analysis (GEPIA), Tumor Immune Estimation Resource (TIMER), and University of Alabama at Birmingham Cancer Data Analysis Portal (UALCAN) databases." (PMID 39310490, 2024).
tumor (1 paper, 2024). "Our findings revealed significant ESRG upregulation in COAD, LUSC, READ, and UCEC; hence, it can be used as a potential diagnostic biomarker to distinguish normal from tumor samples." (PMID 39310490, 2024). "ESRG gene was proposed to have tumor suppressive effect; relating to its interaction with chromatins, different RNA types, and RNA binding proteins (RBP), which are viewed as critical elements in posttranscriptional gene regulation." (PMID 39310490, 2024). "ESRG gene has the ability to interact with chromatins, different RNA types, and RNA binding proteins (RBP); thus making ESRG be considered an oncogenic lncRNA, where its expression is detected in various tumor tissues." (PMID 39310490, 2024). "Additionally, with B cells in LGG, this significant correlation implies the potential immunosuppressive effects of ESRG, contributing to immune evasion and tumor progression." (PMID 39310490, 2024).
ESRG also shares sentences with these, for which no sentence is quoted: brain tumors (1 paper); esophageal carcinoma (1); germinoma (1); head and neck squamous cell carcinoma (1); lung adenocarcinoma (1); thyroid carcinoma (1); uterine carcinosarcoma (1).